HIF1A (hypoxia inducible factor 1 subunit alpha)
Diseases named in the same sentence as HIF1A in open-access papers (continued):
Sharing a sentence is not in itself a finding about the gene and the disease.
tumor (continued). "Hence, based on the construction of a hypoxia-induced CC cell model in vitro and a CC tumor xenografts model in vivo, this study was aimed at exploring that whether BHLHE41 overexpression could alleviate the malignant behavior of hypoxia-induced CC by regulating the HIF-1α/EMT pathway." (PMID 35615737, 2022). "To evaluate the influence of HIF-1α on 5-FU resistance of CRC cells in vivo environments, we established subcutaneous transplantation tumor models of WT and 5-FU-R HCT8 cells with or without stable HIF1A knock-down in nude mice." (PMID 34998404, 2022). "HIF-1α mediated mechanisms favor up-regulation and down-regulation of genes involved in tumor growth and malignant progression as well as epigenetic modification, while HIF-2α stimulates some, but not all, genes activated by HIF-1α." (PMID 36226050, 2022). "Of the 1004 tumours available in the TMA, 985 were successfully stained and evaluated for HIF-1α, where 698 (71%) were HIF-1α negative." (PMID 35140341, 2022). "Under normal or hypoxic conditions, HIF-1α can regulate CAIX overexpression, which can not reflect tumor hypoxia by testing CAIX expression level, and can not predict the prognosis of patients." (PMID 36542612, 2022). "HIF-1α and GLUT-1 were expressed by tumor cells in nearly all cytological cases, regardless of tumor type, although to different extents." (PMID 36620569, 2022). "Our results show highly elevated expression levels of HK2 and HIF1A in PHCs and HCC-PHHs in comparison to non-HCC-PHHs, indicating a hypoxic (peri-)tumor environment." (PMID 36077764, 2022). "Fifth, not only tumour growth but also chemosensitization after HBO is ascribed to the downregulation of both HIF1α and HIF2α but not the downregulation of HIF1α or HIF2α individually." (PMID 33986256, 2021). "Immunohistochemistry analysis of mouse subcutaneous tumor and HCC samples showed low NONO expression had lower HIF-1α, HIF-2α, GLUT1 and VEGF expression, indicated that NONO was closely related to the HIF transcription network." (PMID 34079086, 2021). "Whereas silencing PFKFB4 showed potent inhibition in ccRCC cells regardless of HIF1A status, PFKFB4-OE did not per se promote tumor growth." (PMID 34593007, 2021). "Even though it had no significant inhibitory effect in tumor growth, BYHWD effectively normalized the tumor microenvironment and vasculature by modulating VEGF, regulator of G protein signaling 5 (RGS-5) and HIF-1α." (PMID 33801741, 2021). "Similarly, in different tumour cell lines a deletion of HIF2α affected cell proliferation conversely, but in spontaneous colorectal cancer HIF2α seems to act rather in a protumorigenic manner, whereas a stabilization of HIF1α did not increase the tumour growth in the mouse models." (PMID 33919829, 2021). "While the interplay between tumor angiogenesis and hypoxia is well-known, the role of ADBR2 in and regulating tumor hypoxia especially through HIF-1α signaling has not been extensively studied in head and neck cancer and warrants further research." (PMID 34790909, 2021). "In tumor cell lines, the absence of SIRT3 led to the overproduction of ROS, resulting in the stabilization of HIF1α and the upregulation of its glycolytic targets." (PMID 34680164, 2021). "Surprisingly, Hif1α−/− PyMT+ mice had a significant increase in the number of metastatic lesions in the lung and total metastatic lesion area, regardless of whether the data were normalized to total tumor weight at end point, the mouse age at sacrifice, or left un-normalized." (PMID 34556788, 2021). "In line with its putative tumor-suppressive role, the absence of HACE1 correlated with enhanced HIF1α protein levels in WT tissues compared to the patient-matched normal kidneys." (PMID 33603169, 2021).
tumor (continued). "Cancer cells at the invasive strand and cancer cells inside the tumor body, which exhibited different cytoplasmic/dot-like SQSTM1 staining, showed similar HIF1α staining intensity (data not shown)." (PMID 34483138, 2021). "HIF-1α and HIF-2α have unique tissue distributions and play critical but non-overlapping roles in tumor progression." (PMID 34684168, 2021). "We found that the non-degradable HIF-1α mutants and TGF-β synergistically promoted tumor formation significantly." (PMID 34930376, 2021). "In vivo analysis identified the role of EGC in inhibiting tumor growth, suppressing LDHA and HIF-1α expression, and triggering apoptosis without detected adverse effects." (PMID 33401572, 2021). "Altogether, these findings indicate that CAV1 function as a tumor suppressor in the absence of E-cadherin, involves NOS inhibition, which reduces HIF1α S-nitrosylation and VEGF expression." (PMID 32825247, 2020). "Of these isoforms, HIF-1α and HIF-2α play pivotal roles in the cellular response to the lack of oxygen and tumor promotion." (PMID 32847073, 2020). "Analyses of TCGA mRNA expression data revealed that HIF2A, but not HIF1A, is more highly abundant in ccRCC in comparison to normal kidney and that HIF2A shows a wide distribution of expression levels amongst tumours." (PMID 32807776, 2020). "Secondary signaling mechanisms due to peroxide generated during the catalytic reaction of LOX, including HIF-1α, and the involvement of LOX in various tumor types, have been reviewed extensively and are not discussed here." (PMID 32708046, 2020). "Interestingly, Beclin1 is considered as a tumor-suppressing gene and as an autophagy initiator; its deficiency, linked with higher angiogenesis and cell proliferation in cancer, is more pronounced under hypoxic conditions, with a consistent increase in the levels of HIF-2α, but not HIF-1α." (PMID 32707662, 2020). "A document in the same year claimed that HIF1α increased in the lack of FLCN and promoted tumor growth." (PMID 32850947, 2020). "In a recent clinical trial of EZN-2968, the antisense oligonucleotide inhibitor of HIF-1α successfully down-regulated both mRNA and protein levels of HIF-1α but failed to reduce the expression of VEGFA in tumor biopsies." (PMID 33351793, 2020). "On the contrary, in hypoxic tumor cells, the BNIP3 promoter can be hypermethylated, resulting in its silencing regardless of HIF-1α expression." (PMID 30939818, 2019). "Compared to 231-EV tumors (empty vector MDA-MB-231 with no shRNA), sublines expressing shRNA downregulating HIF-1α, HIF-2α or both isoforms of HIF showed delayed onset of tumor growth as well as growth rate." (PMID 29632647, 2018). "HIF-1α and HIF-2α contribute to tumor progression, whereas HIF-3α is a negative controller of HIF-1α, while the role of HIF-3a on the endogenous feedback regulatory loop under hypoxia is not well determined yet." (PMID 29953500, 2018). "Intrinsic markers that report on hypoxia-induced molecular events (e.g., HIF-1α, GLUT1, CAIX, osteopontin expression) rather than hypoxia itself have been employed as markers of tumor oxygenation with a variable specificity." (PMID 29515786, 2018). "HIF-1α and HIF-2α are known to play important roles in tumour progression under hypoxic conditions, but they have not been studied exhaustively with respect to CD133 expression." (PMID 29492900, 2018). "It is generally accepted that the overexpression of the multidrug resistance proteins of tumor cells such as MDR1, MRP1, BCRP, and HIF-1α mediate multidrug resistance, although its mechanism is not yet clear." (PMID 29416753, 2018).
tumor (continued). "Growing solid tumors reach hypoxia because the blood supply in their normal development state is lacking, which induces the expression of HIF-1α and HIF-2α and contributes to the growth of the tumor in this condition." (PMID 28599281, 2017). "By measuring the levels of HIF-1α protein in the 21 pairs of HCC samples and adjacent noncancerous tissues, we found that HIF-1α were upregulated in the tumor tissues, indicating that HCC tissues were anoxic." (PMID 28596599, 2017). "SAHA has been shown to decrease levels of HIF-1α and VEGF in various tumor cell lines without a proportional change in the levels of HIF-1α mRNA." (PMID 28915577, 2017). "Moreover, in vivo reconstitution of MC38 tumours in HIF-1α KO mice with sVEGFR1 rescued the vascular phenotype and tumour growth, whereas NK cell depletion of established tumours reduced sVEGFR1 levels, which led to non-productive angiogenesis and a decrease in tumour size." (PMID 29150606, 2017). "Accordingly, significant overlapping exists between over-expression of HIF-1α and CAIX, but not HIF-1α and MCT1 or MCT4, in tumor cells." (PMID 28099149, 2017). "It is probable that these tumors did not express HIF-1α because they did not experience HPX, most likely attributable to their better-developed blood vasculature afforded by slower tumor growth." (PMID 28750639, 2017). "While analysis of the tumor initiation phase showed comparable inflammation after MCA-injection, metabolism of MCA was impaired in the absence of Hif-1α." (PMID 27015123, 2016). "Although our in vitro and in vivo findings have established that increased HIF-1α levels, generated by DKG, are indispensable for the DKG-promoted tumor expansion, we cannot rule out the potential contribution of other α-KG-dependent enzymes." (PMID 27058900, 2016). "Correlation of expression of HIF-1α in PTC tissues was not seen between the larger (≥1) and smaller (<1) tumor size (P = 0.782); however, significant differences were observed in HIF-2α expression (P = 0.043)." (PMID 26846782, 2016). "To study the long-term growth pattern of tumor cells in vitro, we successfully generated stable shRNA vector-transfected cells termed sh-HIF-1α No.1, sh-HIF-1α No.2 and sh-NC (negative control vector)." (PMID 26497365, 2016). "In contrast, nuclear HMGB1 localisation was predominantly observed in HIF-1α-negative areas of the tumour, and no evident co-labelling of anti-HMGB1 and HIF1α antibodies was observed in such areas." (PMID 27426915, 2016). "Interestingly, the hypoxia-inducible factors (HIF)-1α and HIF-2α are expressed differentially in M1- and M2-polarized macrophages and regulate inducible NOS-2 (M1) and Arg-1 (M2), respectively, suggesting that tumor hypoxia may mediate the transition of M1 to M2." (PMID 27191744, 2016). "Seven weeks following Ad-Cre injection, KPA tumours had significantly greater mass, indicating that the effects of HIF-2α deletion are not due to HIF-1α-mediated compensation." (PMID 26837714, 2016). "Expression of HIF-1α and CXCL8 was higher in HCC tissues compared to adjacent non-tumor liver tissues." (PMID 26078356, 2015). "HIF-1α and CXCL8 are negative prognostic factors, biological markers of tumor invasiveness and therapeutic targets." (PMID 26078356, 2015). "As a consequence, activation of HIF-1α via inactivation of the VHL gene has been referred to as pseudohypoxia, as opposed to true tumor hypoxia where increased levels of HIF-1α also play a major role [see, for example, 14]." (PMID 25859558, 2015). "In the case of HER2 amplified tumors where hypoxia is not a prominent histologic feature, HIF-1α appears to act in concert with HER2, contributing to aggressive tumor biology." (PMID 26046764, 2015). "Tumour xenografts created from MDA-MB-468 cells showed the same pattern as that seen in spheroids; there was increased hydroxylated HIF-1α at Pro564, but none detectable at Pro402." (PMID 24563687, 2014).
tumor (continued). "Firstly, a significant correlation between tumor-free survival and the expression level of BAG3 and/or HIF-1α is not observed." (PMID 24895585, 2014). "In a sample with very high stroma and tumor cell HIF-1α expression, HIF-1α and MME staining overlapped in stroma cells, but not in tumor cells." (PMID 24460801, 2014). "The model for the case of DTX treatment was validated by comparing the simulation with experimental results for tumor growth under DTX treatment, with or without macrophage HIF-1α or HIF-2α." (PMID 25295611, 2014). "HIF-1α and HIF-2α are structurally similar in their DNA binding and dimerization domains; however, they can play nonoverlapping roles in tumor progression due to their unique target genes and different oxygen requirements for activation." (PMID 24738058, 2014). "While highly homologous, HIF-1α and HIF-2α have unique tissue distributions and play critical but nonoverlapping roles in tumor progression." (PMID 24288553, 2013). "Although highly homologous, HIF-1α and HIF-2α play critical but nonoverlapping roles in tumor progression." (PMID 24288553, 2013). "Despite an initial report showing that HIF-1α would act as a negative factor for the growth of ES cell-derived tumors, some studies support the model that the lack of HIF-1α inhibits tumor growth." (PMID 23300831, 2012). "Tanshinone IIA alleviated residual tumor hypoxia and suppressed epithelial-mesenchymal transition (EMT) in vivo; however, it did not downregulate hypoxia-inducible factor 1α (HIF-1α) or reverse EMT of tumor cells under hypoxic conditions in vitro." (PMID 23137165, 2012). "HIF-1α-dependent effects on sphere formation efficiency in vitro and TIC activity in vivo were observed using parental tumor cells without first enriching for a putative CSC subpopulation based on cell surface markers." (PMID 22225988, 2012). "The first is the A498 cell line, which is a VHL tumor suppressor gene mutant and in which hypoxia-inducible factor (HIF)-2α is activated, although HIF-1α is absent." (PMID 22965141, 2012). "The biological roles of HIF-1α and HIF-2α under hypoxia is controversial; however, HIF-2α, but not HIF-1α, is considered to be important in tumor formation, by promoting Myc activity." (PMID 22768190, 2012). "To test this postulation, we found that HIF-1α siRNA significantly inhibited the expression of HIF-1α and VEGF and tumor angiogenesis without the change of phospho-AKT and phospho-ERK expression." (PMID 21544242, 2011). "This is further supported by data that mutating the FIH-1 target residue in HIF-2α did not increase its effect on HIF target genes or tumour growth in CCRCC cells, whereas substituting the equivalent residue in HIF-1α had a major effect." (PMID 21386837, 2011). "HIF-1α only showed a trend towards higher expression in node positive patients (p = 0.06), although HIF-1α expression was only found in one node negative tumor." (PMID 21569415, 2011). "Correspondingly, separate studies indicate that HIF-2α, but not HIF-1α, contributes to the growth of VHL null tumor xenografts." (PMID 21695080, 2011). "PHD2 is involved in hydroxylation and consequentially degradation of HIF-1α; we found that BMP2 induced increase of PHD2 protein level, in both normal and tumour cells, but this upregulation does not seem to be related to increased protein translation." (PMID 19587783, 2009). "Combined inhibition of HIF-1α and TGF-β in the tumor cells had no additional effect, suggesting parallel roles for hypoxia and TGF-β signaling in tumor cells." (PMID 19727403, 2009).
tumor (continued). "Thirty three tumour samples were classified as HIF-1α protein "positive" (60%%) and 22 as HIF-1α protein "negative" as they did not stain at all (40%)." (PMID 19014607, 2008). "The 126 patients were again divided into four populations based on HIF-1α expression and p21 expression, and we examined the relationship between HIF-1α expression and prognosis in p21-positive or -negative tumor samples." (PMID 17166265, 2006). "The quantification of JAK2 in the HIF1A-negative tumor showed the low expression of JAK2 protein compared to control tissue; however, in the HIF1A-positive tumor, the strong expression of JAK2 was observed compared to HIF1A-negative tumor (p < 0.001)." (PMID 40332447, 2025). "In addition, the systemic delivery of NO significantly downregulated HIF-1α levels, reversed hypoxia-induced DOX resistance, and enhanced anti-tumor immune responses by reprogramming the tumor immune microenvironment." (PMID 40284275, 2025). "Notably, copper chelator treatment alone was not sufficient to fully deplete copper in tumour cells, possibly due to compensatory mechanisms such as transporter protein plasticity (CTR1/ATP7A, etc.)and HIF-1α-mediated glycolytic metabolic reprogramming." (PMID 40809021, 2025). "Their work further revealed that HIF2A, but not HIF1A, was essential for ALK+ ALCL tumor growth." (PMID 40734623, 2025). "In NPC, the anti-cancer HIF-1α is not usually expressed, while HIF-2α, a transcriptional regulator with oncogenic effects, regulates downstream processes involved in angiogenesis, glucose metabolism, and tumor growth target genes." (PMID 38234672, 2024). "Non-neoplastic astrocytes facilitate tumor growth, realizing anti-inflammatory cytokines such as transforming growth factor beta (TGF-β), interleukin 10 (IL-10), and granulocyte colony-stimulating factor (G-CSF), and promote expression of HIF-1a." (PMID 39768176, 2024). "The CAFs-specific deletion of HIF2A, but not HIF1A, suppressed PDAC tumor progression and growth." (PMID 38892190, 2024). "Additionally, administration of DYB‐03 did not have a significant inhibitory effect on tumor growth in A549 double knockdown cells, indicating that DYB‐03 exerts antitumor activity by targeting HIF‐1α and EZH2." (PMID 38072662, 2024). "Although it is not yet clear whether the expression of HIF-1α in NK cells has a promoting or impairing effect on NK cell effector function, downregulation of HIF-1a signaling within the tumor itself can also enhance immune activity." (PMID 38433193, 2024). "Stable expression of nondegradable HIF-1α only partially rescued proliferation in IMS-Prdx5-expressing cells, indicating that mitochondrial H2O2 signaling contributes to tumor cell proliferation and survival through HIF-dependent and HIF-independent mechanisms." (PMID 36935009, 2023). "HIPK2 overexpression reduces the basal levels of HIF-1α with a mechanism that does not involve hypoxia, inhibiting the HIF-1 transcriptional activity and, therefore, counteracting theHIF-1-induced angiogenesis and tumor progression, in vitro and in vivo." (PMID 37345014, 2023). "Notably, the expression of ALKBH5 or HIF1α was increased in PC tissues, while the expression of HDAC4 was not significantly different between normal and tumor tissues." (PMID 37149664, 2023). "In addition to VEGF, VEGF receptor-2 (VEGFR)-2, and CA9, which are regulated by hypoxia-inducible factor 1 subunit alpha (HIF-1a), exosomes have emerged as a novel source of non-invasive tumor biomarkers." (PMID 37762660, 2023).